FOXM1 (forkhead box M1)
Diseases named in the same sentence as FOXM1 in open-access papers (continued):
Sharing a sentence is not in itself a finding about the gene and the disease.
glioblastoma (139 papers, 2009 to 2025). The most malignant astrocytic tumor (WHO grade IV). "Beyond TNBC, FOXM1 is implicated in other solid cancers, such as brain (glioblastoma), lung, and pancreatic cancers, and is considered an Achilles’ heel of aggressive cancers." (PMID 39594778, 2024). "ALKBH5 promoted cancer stem cell self‐renewal in acute myeloid leukaemia, and caused glioblastoma tumourigenesis by sustaining FOXM1 expression." (PMID 36864711, 2023). "Recently, increasing evidence has implicated elevated FOXM1 expression in a variety of tumor types and correlates with tumorigenicity and a poor prognosis, including glioblastoma multiforme." (PMID 34740322, 2021). "Decreased m6A modification levels of FOXM1 result in enhanced FOXM1 expression levels, which ultimately cause glioblastoma." (PMID 30031372, 2018). "Notably, ZEB1 and Twist1 were recently identified as downstream targets of fibroblast growth factor receptor 1 (FGFR1)/forkhead box M1 (FOXM1) in glioblastoma, and their expression is highly associated with resistance to radiotherapy." (PMID 31234336, 2019). "In a recent study to evaluate early changes in expression in glioblastoma cells after radiation, we determined that down-regulation of genes implicated in the cell cycle, DNA repair and DNA replication is likely the result of decreased expression of FOXM1, E2F1, E2F2 and E2F8." (PMID 33804958, 2021). "This study provides important findings on FoxM1 role in glioblastoma cells, setting the stage for future research with significant implications for the development of targeted therapeutic strategies for treating GBM." (PMID 41323781, 2025). "Glioblastoma cell resistance to temozolomide is mediated by CXCL12 by forkhead box protein M1 (FOXM1) up-regulation." (PMID 40076892, 2025). "Our previous studies also showed that YBX1 binds and promotes the stability of mRNAs such as FOXM1 in glioblastoma cells." (PMID 40819060, 2025). "In xenograft models of glioblastoma, the FoxM1-Sox2 pathway has been shown to be involved in the radiotherapy response." (PMID 40002588, 2025). "ALKBH5 accelerates tumor growth in glioblastoma (GBM) by enhancing FOXM1 expression through the removal of m6A." (PMID 41446042, 2025). "Knockdown of FOXM1 expression by siRNA in glioblastoma cells inhibits VEGF secretion and capillary tube formation." (PMID 39594778, 2024). "POLE2 promotes the malignant phenotype of glioblastoma by promoting AURKA-mediated stabilization of FOXM1." (PMID 37880682, 2023). "ALKBH5 can stabilize the expression of the target gene FOXM1 mRNA by reducing the levels of m6A, thereby inducing the occurrence of glioblastoma." (PMID 37805597, 2023). "In glioblastoma stem cells, FOXM1 is phosphorylated by and associates with maternal embryonic leucine-zipper kinase (MELK), and both events are necessary for a MELK–FOXM1 protein complex to bind the EZH2 promoter and stimulate its transcription." (PMID 37686402, 2023). "TRIM56 has also been shown to increase FOXM1 protein levels, enhance the stability of FOXM1 by de-ubiquitination, and promote DNA damage repair through FOXM1 in glioblastoma cells." (PMID 36471347, 2022). "m6A demethylation on forkhead box M1 (FOXM1) mRNA maintains the tumorigenesis of glioblastoma stem-like cells." (PMID 36557225, 2022). "The expression of ALKBH5 is correlated with poor prognosis in glioblastoma and promotes the proliferation and tumor progression of glioblastoma stem cells by enhancing FOXM1 expression." (PMID 36360287, 2022). "In glioblastoma cells, PARP3 was proposed to enhance the transcriptional activity of FOXM1 to confer glioblastoma cell radioresistance." (PMID 36109561, 2022). "Formerly, circ-FOXM1 has been identified to exert the carcinogenic effects in several kinds of cancers such as glioblastoma, non-small cell lung cancer and papillary thyroid cancer." (PMID 35799265, 2022).
glioblastoma (continued). "And ALKBH5 was highly expressed in glioblastoma stem-like cells (GSCs) and maintained tumorigenic activity of GSCs via maintaining FOXM1 expression and cell proliferation program." (PMID 35444654, 2022). "RNA demethylase ALKBH5 is highly expressed in glioblastoma stem cells (GSCs) and promotes tumorigenicity through the binding mRNA of the FOXM1 transcription factor by interacting with lncRNA FOXM1-AS." (PMID 36012529, 2022). "For instance, ALKBH5 has been shown to maintain the tumorigenicity of glioblastoma stem-like cells by sustaining FOXM1 expression and cell proliferation program." (PMID 35031597, 2022). "Presently, circ-FOXM1 has been proven to be upregulated in glioblastoma as screened by circRNA microarray." (PMID 35799265, 2022). "By analyzing samples from the TCGA database and clinical specimens, our data demonstrated that elevated expression of NOX4 and FOXM1 predicted a worse prognosis of glioblastoma." (PMID 34740322, 2021). "Our results collectively indicate that circPIK3C2A functions as ceRNA by mediating miR-877-5p/FOXM1 axis, providing a novel perspective of applying CircPIK3C2A in the clinical intervention of glioblastoma in the future." (PMID 35004326, 2021). "Overexpression of NOX4 or FOXM1 promoted aerobic glycolysis, whereas knockdown of NOX4 or FOXM1 significantly suppressed aerobic glycolysis, in glioblastoma cells." (PMID 34740322, 2021). "ALKBH5 has been reported to demethylate FOXM1 nascent transcripts and promote FOXM1 expression in glioblastoma." (PMID 33428593, 2021). "FOXM1 is a pro-oncogenic transcription factor that is overexpressed in glioblastoma multiforme (GBM) and correlated with increased RAD51 expression." (PMID 34208195, 2021). "The functions of NOX4 and FOXM1 in aerobic glycolysis in glioblastoma cells were determined by a series of experiments, such as Western blot, extracellular acidification rate (ECAR), lactate production, and intracellular ATP level assays." (PMID 34740322, 2021). "ALKBH5 regulates FOXM1 expression by demethylating the nascent transcripts of FOXM1 in glioblastoma stem-like cells." (PMID 33428593, 2021). "Together, these findings reveal that NOX4-derived ROS, especially from mitochondria, are required for an increase in FOXM1 levels in glioblastoma cells." (PMID 34740322, 2021). "We then evaluated the potential mechanisms responsible for the expression of FOXM1 in glioblastoma cells." (PMID 34740322, 2021). "Accordingly, the depletion of ferritin in glioblastoma stem-like cells affected their proliferation/cell cycle progression through the STAT3-Forkhead box protein M1(FOXM1) regulatory axis, revealing an iron-regulated CSC pathway." (PMID 34831207, 2021). "To identify FOXM1 transcriptional activity in hypoxic glioblastoma cells, we focused on and investigated the protein expression of PLK1 and cyclin B1, two well-known downstream targets of FOXM1." (PMID 34740322, 2021). "We also extended our analysis to hypoxic conditions by detecting FOXM1 expression in glioblastoma cells exposed to severe hypoxia or normoxia for 48 h." (PMID 34740322, 2021). "ALKBH5-induced overexpression of FOXM1 contributes to the tumorigenicity of glioblastoma stem-like cells." (PMID 34491904, 2021). "Recently, a study has demonstrated that the m6A demethylase ALKBH5 served as a negative prognostic biomarker for GBM patients and maintained the tumorigenicity of glioblastoma stem cell–like cells by activating FOXM1 expression and cell growth." (PMID 34150845, 2021). "Collectively, from both gain-of-function and loss-of-function studies, our data suggest that both NOX4 and FOXM1 play essential roles in regulating aerobic glycolysis and proliferation in glioblastoma cells." (PMID 34740322, 2021). "We also showed that FOXM1 strongly promoted aerobic glycolysis, which has seldom been discussed in glioblastoma before." (PMID 34740322, 2021).
glioblastoma (continued). "Here, the authors show that AVIL, an actin regulatory protein, is overexpressed in glioblastomas and mediates oncogenic effects through regulation of FOXM1 stability and LIN28B expression." (PMID 32651364, 2020). "In glioblastoma, FOXM1 has been shown to promote stemness by modulating SOX2 expression in vitro and in vivo, and in neuroblastoma cells, FOXM1 was shown to directly activate SOX2 expression." (PMID 32210076, 2020). "FOXM1 expression in glioblastoma stem like cells has been shown to be elevated via FGFR signaling, wherein the expression of FGFR has been found to be elevated via α6-integrin and ZEB1/YAP1 transcription factor complex." (PMID 33680951, 2020). "AlkB Homolog 5 (ALKBH5), an m6A demethylase, facilitates glioblastoma proliferation by demethylating the transcripts of forkhead box protein M1 (FOXM1), an important cell cycle regulator." (PMID 32267835, 2020). "Forkhead Box protein M1 (FOXM1) abundance was increased when ALKBH5 was upregulated in glioblastoma." (PMID 31931709, 2020). "CDK4 and CDK6 activate FOXM1, and FGFR1 appears to be involved in FOXM1 expression since silencing of FGFR1 in glioblastoma cells resulted in downregulation of FOXM1." (PMID 32976773, 2020). "ALKBH5 also maintains tumorigenicity of glioblastoma stem-like cells by sustaining FOXM1 expression and cell proliferation program." (PMID 33489865, 2020). "More recently, FOXM1 was shown to play a critical role in the maintenance of Glioblastoma stem cell." (PMID 32066721, 2020). "For instance, ALKBH5 has been shown to sustain the tumorigenicity of glioblastoma stem-like cells by demethylating FOXM1 nascent transcripts and thus enhancing FOXM1 expression." (PMID 31856849, 2019). "In glioblastoma, elevated ALKBH5 reduces m6A methylation and facilitates expression of oncogene FOXM1, leading to enhancement of glioblastoma stem-like cells (GSCs) self-renewal and tumorigenicity." (PMID 31801551, 2019). "Recently, the other demethylase, ALKBH5, was shown to potentiate tumourigenicity of glioblastoma by enhancing FOXM1 expression." (PMID 31632489, 2019). "Using RNA-sequencing and western blotting analyses, we also found that AKBA arrested the cell cycle at the G2/M phase by regulating the p21/FOXM1/cyclin B1 pathway and inhibited mitosis of glioblastoma cells by downregulating the Aurora B/TOP2A pathway." (PMID 29970196, 2018). "FOXM1, known for regulating the cell cycle via transcription of G1/S and G2/M transition factors, is upregulated in a multitude of cancer including glioblastoma." (PMID 30167084, 2018). "For example, pGENMi reported FOXM1 as a top scoring association for the drug temozolomide; this prediction was validated by a study where siRNA knockdown of FOXM1 was shown to sensitize recurrent glioblastoma multiforme (GBM) tumors to this drug." (PMID 29898900, 2018). "Last, FOXM1 stimulates self-renewal, tumorigenicity and invasiveness of glioblastoma stem-like cells by transactivating a number of molecules, including IPO7 (importing-7), CDC20, PDGF-A, ANXA1, MMP-2 and VEGF." (PMID 27259253, 2016). "One study has shown that FoxM1 (Forkhead box protein M1) activated the expression of Skp2 in glioblastoma." (PMID 26046466, 2015). "Our results indicate that suppression of FoxM1 expression inhibit Anxa1 expression in glioblastoma cells." (PMID 23991102, 2013). "For instance, Rad51, another critical protein required for efficient HR repair, contains 2 forkhead-binding sites in its promoter, and has also been described as a transcriptional target of FoxM1 in glioblastoma cells." (PMID 23467617, 2013). "Significantly higher expression of both FoxM1 and Anxa1 were evident in LN-229and U-87MG glioblastoma cells than in Hs683 and SW1088 cells." (PMID 23991102, 2013). "The publically available human glioblastoma microarray data also showed correlation between FoxM1 and Anxa1 expression (n = 98, r = 0.327, P<0.0001)." (PMID 23991102, 2013).
glioblastoma (continued). "Our results indicate that inhibition of FoxM1 expression significantly suppresses the tumorigenicity of human glioblastoma cells, whereas rescue the Anxa1 expression can recover the ability of tumorigenicity." (PMID 23991102, 2013). "FoxM1 has also been linked to genotoxic drug resistance in glioblastoma multiforme (GBM)." (PMID 23467617, 2013). "Furthermore, Ena15/Ena21 inhibits the cell proliferation of glioblastoma multiforme-derived cell lines, increases m6A levels and stabilizes forkhead box M1 (FOXM1) mRNA." (PMID 41373022, 2025). "A recent study reported that ALKBH5 could demethylate FOXM1 nascent transcripts, thus increasing FOXM1 expression so as to promote tumorigenesis and development of glioblastoma." (PMID 40846737, 2025). "In glioblastoma, FOXM1 expression is up‐regulated by m6A demethylase ALKBH5." (PMID 38967523, 2024). "The interaction of BUB1b with FOXM1 enhanced radiotherapy resistance in glioblastoma." (PMID 39043653, 2024). "Furthermore, in glioblastoma, FOXM1 has been shown to promote tumorigenesis by mediating the nuclear translocation of β-catenin in the absence of conventional Wnt/β-catenin pathway activation." (PMID 37817774, 2023). "TRIM56 may therefore suppress the radiosensitization of human glioblastoma by regulating FOXM1-mediated DNA repair." (PMID 36471347, 2022). "It has been reported that FOXM1 strongly enhances the nuclear translocation of β-catenin in normal cells and cancer cells, and nuclear shuttling of β-catenin by FOXM1 is commonly observed in many cancers such as glioblastoma, meningiomas, and pancreatic ductal adenocarcinoma." (PMID 35053606, 2022). "A study reported that ALKBH5 could maintains tumorigenicity of glioblastoma stem-like cells by sustaining FOXM1 expression." (PMID 36008805, 2022). "It is upregulated in glioblastoma where it might promote tumor cell proliferation via the MYCNOS/miR-216B/FOXM1 axis." (PMID 35585970, 2022). "Although we investigated the regulatory role of FOXM1 in aerobic glycolysis in glioblastoma cells, more studies are needed to explore whether FOXM1 regulates other glycolysis enzymes, and the underlying mechanism should be elucidated." (PMID 34740322, 2021). "To test this hypothesis, we investigated the roles of NOX4 and FOXM1 and their relationship in glioblastoma cells with in vitro and in vivo experiments." (PMID 34740322, 2021). "Increased expression of FOXM1 induced by NOX4-derived MitoROS plays a pivotal role in aerobic glycolysis, and our findings suggest that inhibition of NOX4-FOXM1 signaling may present a potential therapeutic target for glioblastoma treatment." (PMID 34740322, 2021). "FOXM1 expression was markedly increased in glioblastoma cells after exposure to hypoxia." (PMID 34740322, 2021). "In addition, FOXM1 protein and mRNA expression levels were dramatically increased in glioblastoma cell lines compared with the normal human astroglia (NHA) cell line." (PMID 34740322, 2021). "However this process was inhibited by the Wnt signaling activation and subsequent interaction with USP5 thereby leading to the stabilization of FOXM1 in glioblastoma multiforme." (PMID 33680951, 2020). "In glioblastoma, inhibition of FOXM1 sensitized tumors to irradiation in vitro and in vivo." (PMID 32210076, 2020). "Similarly, silencing ALKBH5 in glioblastoma stem cells suppressed cell proliferation via enhancing FOXM1 expression." (PMID 31333841, 2019). "The data are consistent with a mechanism in which AKBA arrested the cell cycle in glioblastoma cells at the G2/M phase by regulating the p21/FOXM1/cyclin B1 pathway, inhibited mitosis by downregulating the Aurora B/TOP2A pathway, and induced mitochondrial-dependent apoptosis." (PMID 29970196, 2018). "Furthermore, ALKBH5 also plays an important role in maintaining glioblastoma proliferation and tumorigenesis by enhancing mRNA expression of FOXM1, a pivotal transcription factor for glioblastoma stem cell self-renewal." (PMID 30212448, 2018).
glioblastoma (continued). "Besides, targeting FOXM1 also sensitized resistant glioblastoma cells to temozolomide by downregulating Rad51." (PMID 24824601, 2014). "Furthermore, FOXM1 could regulate glioblastoma cell proliferation and progression by modulating some cell cycle-related genes required for G1/S and G2/M42." (PMID 35978634, 2022). "BUB1 (budding uninhibited by benzimidazoles 1) plays a key role in the proliferation and radioresistance of glioblastoma (GBM) in a FOXM1-dependent manner." (PMID 33644115, 2021). "However, the roles of FOXM1 in metabolic changes in glioblastoma have yet to be fully elucidated." (PMID 34740322, 2021). "We further investigated whether NOX4 and FOXM1 influence glioblastoma proliferation." (PMID 34740322, 2021). "Since our results clearly demonstrated that NOX4 regulates aerobic glycolysis in glioblastoma cells via FOXM1 and that increased glucose metabolism is advantageous for in proliferating cells, we further explored whether FOXM1 is critical for NOX4-regulated cancer proliferation." (PMID 34740322, 2021). "Besides, the inhibition of ALKBH5 could reduce the proliferation of glioblastoma stem-like cells via FOXM1 axis." (PMID 33240891, 2020). "FOXM1 could also be activated via CXCL12 mediated PI3K/AKT-dependent mechanism in glioblastoma." (PMID 33680951, 2020). "We have also found that LCS1269 triggered G2 cell cycle block associated with Wee1/Myt1 axis activation, the upregulation of transcription factor Forkhead Box M1 (FOXM1), and its target Polo Like Kinase 1 (PLK1) in human glioblastoma cell lines." (PMID 40649791, 2025). "For example, in glioblastoma, ALKBH5 maintains tumorigenicity of cancer stem-like cells by inducing the expression of FOXM1." (PMID 40603319, 2025). "Expression of Forkhead box protein M1 (FOXM1), a downstream target of HIF-1α39 that has been shown to play multiple roles in glioblastoma, was downregulated following BCAT1 knockdown and this was accompanied by downregulated expression of its target genes." (PMID 37885806, 2023). "In glioblastoma stem cells, the m6A demethylase ALKBH5 interacts with lncRNA Forkhead box protein M1(FOXM1)-AS for the purpose of promoting cancer cell growth and tumorigenicity." (PMID 36935487, 2023). "In glioblastoma, ALKBH5 promotes tumor growth by lowering the m6A methylation in target mRNA transcripts and increasing the FOXM1 expression." (PMID 37325047, 2023). "In addition to FTO, m6A eraser ALKBH5 drove proliferation in glioblastoma stem cells by demethylating nascent mRNA transcripts of Foxm1, a transcription factor involved in cell-cycle control and proliferation, resulting in increased FOXM1 expression and activity in an m6A-dependent manner." (PMID 35350378, 2022). "ALKBH5 has been verified to demethylate FOXM1 nascent transcripts by the FOXM1 3′-UTR region, resulting in enhanced FOXM1 expression in glioblastoma stem-like cells." (PMID 35279083, 2022). "In glioblastoma multiforme cells, CXCL12/CXCR4 upregulates FOXM1 expression, promoting tumor migration and invasion." (PMID 36591565, 2022). "Each of these transcription factors harbors oncogenic or tumor-promoting functions and some of them were reported to be overexpressed in cancer, including overexpression of E2F1, E2F6, FOXM1, and MYBL2 in glioblastomas." (PMID 35228525, 2022). "Moreover, Forkhead box M1 (FOXM1) transcriptionally activates the expression of IPO7 to promote the nuclear import of glioma-associated oncogene homolog 1 (GLI1), and this biological process modulates the growth, migration, and invasion of glioblastoma multiforme cells in vitro." (PMID 35588577, 2022).